LARP6 (La ribonucleoprotein 6, translational regulator)
Diseases named in the same sentence as LARP6 in open-access papers:
LARP6 is named in the same sentence as 26 diseases in open-access papers, as found by Europe PMC text mining. Sharing a sentence is not in itself a finding about the gene and the disease. The quoted sentences say what the papers report.
Hepatic fibrosis (5 papers, 2013 to 2026). The presence of excessive fibrous connective tissue in the liver. "We also found an increase in LARP6 in the 30d EtOH mice; LARP6 is a positive regulator of collagen expression, and inhibition of LARP6 decreases hepatic fibrosis resulting from alcohol exposure." (PMID 38132102, 2023). "This makes LARP6 a promising target for liver fibrosis, and a recent high throughput screen has yielded a compound (C9) that represents the first LARP6 inhibitor with significant antifibrotic activity." (PMID 34588551, 2021). "Our results suggest LARP6 plays a key role in fibrogenic gene regulation and that targeting LARP6 in human HSCs may represent a therapeutic approach for liver fibrosis." (PMID 41746718, 2026). "We identified 61 liver fibrosis-associated genes (e.g., AEBP1, PRRX1 and LARP6) that may serve as a repertoire of translatable drug target candidates." (PMID 34588551, 2021).
breast carcinoma (4 papers, 2019 to 2025). "In human breast cancer, LARP6 overexpression is associated with epithelial-to-mesenchymal transition (EMT)." (PMID 36052258, 2022). "In human breast carcinomas, higher LARP6 expression is associated with the invasive mesenchymal-like subtypes." (PMID 33171110, 2020). "However, the upregulation of LARP6 in TNBC suggests that it has subtype‐specific roles in this breast cancer variant." (PMID 40635123, 2025). "The relationship with undifferentiated M0 macrophages and negative correlation with CD4+ non‐regulatory T cells points to a complex immunomodulatory role for LARP6 in shaping the breast cancer microenvironment that warrants further mechanistic studies." (PMID 40635123, 2025). "Following these observations, we further examined the expression of LARP6 in cell lines from different breast cancer subtypes." (PMID 40635123, 2025). "Our analysis also revealed distinct correlation patterns between LARP6 expressions and various immune cell infiltrates in the breast cancer microenvironment." (PMID 40635123, 2025). "Based on the immune cell infiltration analysis, LARP6 simultaneously modulates the tumour immune microenvironment in breast cancers." (PMID 40635123, 2025). "Among them, LARP6 has been implicated to be upregulated in basal‐like invasive ductal carcinomas of the breast, and ectopic expression of LARP6 in breast cancer cells enhances proliferation and invasion." (PMID 40635123, 2025). "Future studies incorporating ChIP‐seq, ATAC‐seq, and transcription factor knockdown experiments across multiple cell lines representing each breast cancer subtype would provide mechanistic insights into the differential regulation of LARP6 expression." (PMID 40635123, 2025). "LARP6 is overexpressed in breast cancer and promotes angiogenesis by upregulating the expression of MMP-9 and VEGF." (PMID 36052258, 2022). "Mining a published proteomics dataset of protein expression levels in a panel of human breast carcinoma cell lines revealed LARP6 protein expression to be mainly detectable in cell lines belonging to the mesenchymal/low Claudin subtype." (PMID 33171110, 2020). "Our thorough RNA‐seq analyses conducted on more than 260,000 cells across various breast cancer subtypes demonstrated that LARP6 expression is notably increased in TNBC compared to ER+ and HER2+ variants, highlighting LARP6 as a potential key regulator of TNBC progression." (PMID 40635123, 2025). "In addition to offering a potentially important link between several known factors of breast cancer risk, our current study also identifies novel functions of PAPP-A, namely the elevation of collagen through LARP6 and the activation of the collagen receptor DDR2." (PMID 31046834, 2019). "Subsequently, we further narrowed down the eight candidate genes (TRIM47, SPHK1, RGMA, ROPN1B, LARP6, ROPN1, NPM2 and LPL) that are shared in TNBC compared to ER+ and HER2+ breast cancer subtypes in cancer cells." (PMID 40635123, 2025). "The high expression level of LARP6 in the TNBC subtype compared to ER+ and HER2+ subtypes, which is correlated with a poor breast cancer survival rate, highlights its potential to be a TNBC specific prognostic marker and a TNBC specific therapeutic target." (PMID 40635123, 2025). "In human breast carcinomas, epithelial-to-mesenchymal transition (EMT) upregulates LARP6 expression to enhance protein synthesis and support invasive growth." (PMID 33171110, 2020). "Furthermore, we found the shared gene, LARP6 (La Ribonucleoprotein 6) was significantly upregulated in TNBC compared to ER and HER2‐positive breast cancers." (PMID 40635123, 2025). "LARP6, an oncogene, is highly expressed in myoepithelial cells and mammary basal cell-like invasive ductal carcinoma of the breast and is also aberrantly expressed in MDA-MB-231 breast cancer cells, promoting cell proliferation." (PMID 36052258, 2022).
colorectal cancer (3 papers, 2023 to 2025). A primary or metastatic malignant neoplasm that affects the colon or rectum. "Additionally, while Larp6 suppressed sphingomyelin synthesis in colorectal cancer, further pathway experiments are essential to confirm its role in myelin regeneration in future." (PMID 41017072, 2025). "In a comparative analysis, Noxa1 was primarily expressed in colorectal cancer tissues, Tmem88 was more prevalent in normal tissues, and Larp6 showed no significant expression differences between the two." (PMID 40084254, 2025).
metabolic dysfunction-associated steatohepatitis (2 papers, 2023 to 2026). Metabolic dysfunction-associated steatohepatitis (MASH, formerly known as nonalcoholic steatohepatitis or NASH) is a type of fatty liver disease. "Other genes that have been implicated in fibrogenesis include AEBP1, PRRX1, and LARP6 in nonalcoholic steatohepatitis (NASH) with fibrosis." (PMID 37569677, 2023). "We demonstrated that LARP6 was upregulated in human activated HSCs in metabolic dysfunction-associated steatohepatitis (MASH) and MetALD." (PMID 41746718, 2026).
Bardet-Biedl syndrome (1 paper, 2017). A ciliopathy with multisystem involvement. "Since Bardet–Biedl syndrome, a ciliopathic human genetic disorder, has been reported to be linked to obesity and diabetes, dysfunction of LARP6 may result in ciliopathies associated with type II diabetes." (PMID 28344782, 2017).
breast tumor (1 paper, 2020). "Similarly, analysis of publicly available mRNA expression data from 1,758 human primary breast tumors revealed a significant upregulation of LARP6 in tumors of the mesenchymal/low Claudin subtype." (PMID 33171110, 2020). "Indeed, immunohistochemistry (IHC) profiling of a panel of human breast tumor tissue samples composed of both metaplastic and non-metaplastic carcinomas revealed a significant association of high LARP6 expression with metaplastic tumors." (PMID 33171110, 2020).
ciliopathies (1 paper, 2017). "Since the molecular mechanisms underlying the structure and function of cilia are well-conserved among the vertebrates, this newly discovered role of LARP6 in ciliated cell differentiation is likely conserved in humans and may be involved in pathogenesis of human ciliopathies." (PMID 28344782, 2017).
fibrosis (1 paper, 2016). the formation of excess fibrous connective tissue in an organ or tissue in a reparative or reactive process. "Based on the importance of LARP6 dependent mechanism of type I collagen production in fibrosis, phosphorylation of LARP6 is currently an active area of research." (PMID 27011170, 2016). "However, in reparative fibrosis (wound healing) or in reactive fibrosis (excessive scarring of organs) the LARP6 mechanism is activated resulting into a synthesis which is better organized and more effective." (PMID 27011170, 2016).
idiopathic pulmonary fibrosis (1 paper, 2023). Idiopathic pulmonary fibrosis (IPF) is a nonneoplastic pulmonary disease that is characterized by the formation of scar tissue within the lungs in the absence of any known cause. "YY1, RTN4, RICTOR, SFPQ, LARP6, and HELLS have been associated with cancers previously and, in this study, exhibited differential level changes between control, Idiopathic Pulmonary Fibrosis (IPF) and lung cancer cells." (PMID 37569873, 2023).
lung carcinoma (1 paper, 2023). "SFPQ, RTN4, HELLS, RICTOR, and LARP6 have high expression in lung cancer and other cancer cells and tissues." (PMID 37569873, 2023).
lupus erythematosus (1 paper, 2012). An autoimmune, connective tissue chronic inflammatory disorder affecting the skin, joints, kidneys, lungs, heart, and the peripheral blood cells. "LARP6 (La-related protein 6 or acheron) is structurally related to La/SSB (Lupus erythematosus and Sjogren Syndrome antigen)." (PMID 22876330, 2012).
lymph node metastasis (1 paper, 2023). "Interestingly, we noted that LARP6 expression is significantly reduced in CRC tissues of primary CRC patients with lymph node metastasis compared with those without lymph node metastasis." (PMID 36691044, 2023).
primary ciliary dyskinesia (1 paper, 2024). A rare, genetically heterogeneous, primarily respiratory disorder characterized by chronic upper and lower respiratory tract disease. "Dynein axonemal assembly factor 6 (DNAAF6), a causative gene of primary ciliary dyskinesia, was isolated as an interacting protein with La ribonucleoprotein 6 (LARP6) that regulates ciliogenesis in multiciliated cells (MCCs)." (PMID 38762183, 2024).
scleroderma (1 paper, 2013). Scleroderma is a rare autoimmune connective tissue disorder characterized by abnormal hardening of the skin and, sometimes, other organs. "To verify that this interaction is not cell type specific we repeated FKBP3/LARP6 pull downs in scleroderma skin fibroblasts with the same result (data not shown)." (PMID 23755290, 2013).
type II diabetes (1 paper, 2017). "Moreover, recent single-nucleotide polymorphisms’ analysis from four genome-wide association studies indicate that a polymorphism at or near LARP6 is linked to the risk of type 2 diabetes." (PMID 28344782, 2017).
cancer (13 papers, 2015 to 2026). A tumor composed of atypical neoplastic, often pleomorphic cells that invade other tissues. "The IDR-mediated RNA-binding selectivity is critical for LARP6-mediated promotion of cancer cell viability and invasion." (PMID 41714637, 2026). "In conclusion, our study reveals LARP6 as an important regulator of TNBC cancer cell proliferation by comprehensive integration of single‐cell RNA sequencing datasets and following differential gene expression analysis and pathway enrichment analysis." (PMID 40635123, 2025). "Firstly, our in vitro studies suggest LARP6 functions in regulating the proliferation of the TNBC cancer cells; the in vivo validation of the LARP6 role will be necessary to investigate the therapeutic potential of targeting LARP6." (PMID 40635123, 2025). "The results revealed LARP6 was highly upregulated in TNBC cancer cells compared to ER+ and HER2+ cancer cells, promoting us to investigate the role of LARP6 in TNBC progression." (PMID 40635123, 2025). "Immune infiltration analysis further revealed that LARP6 expression correlates with distinct immune cell populations in the tumour microenvironment, suggesting its role beyond cancer cell intrinsic functions." (PMID 40635123, 2025). "Further, they have revealed an elegant mechanism of modulating ribosome production involving the mRNA binding protein LARP6, which is a promising therapeutic target to specifically inhibit invasive cells in cancer (Dermitet al., 2020)." (PMID 38628976, 2023). "Our findings reveal LARP6-mediated mRNA localization as a key regulator of ribosome biogenesis during cell migration and demonstrate a role for this process in cancer progression downstream of EMT." (PMID 33171110, 2020). "Five mutated gene variants that were transferred to the BRCA1-KO fibroblasts (BTN3A2, DDX51, LARP6, AP1G1 and COL18A1) were found to be also present as RNA variants following RNA sequencing of BRCA1-KO fibroblasts after exposure to cancer EVs." (PMID 31200749, 2019). "Overall, these results provided the first evidence that this orally bioavailable Akt inhibitor, currently in phase II clinical trials for cancers, inhibits type I collagen production by inhibiting LARP6 phosphorylation." (PMID 26932461, 2016). "LARP6, as well as post-transcriptionally driving collagen synthesis which is an essential cytoskeletal component of the migrating cancer cell, also regulates gene transcription and LARP4b regulates the transcription factor C/EBPα." (PMID 26501340, 2015). "Therapies to attenuate pathological upregulation of La, LARP1 or LARP6 are likely to have profound anti-proliferative and pro-apoptotic effects in cancer cells." (PMID 26501340, 2015). "Additionally, we performed CCK‐8 assay and EdU incorporation assay to explore the role of LARP6 in cancer cell proliferation." (PMID 40635123, 2025). "In contrast to the known link of LAPR6 to cancer progression, the direct association between LARP6 function and bone metabolism has not yet been elucidated in detail." (PMID 39408753, 2024). "Studying translation regulation also holds the promise of uncovering new potent therapeutic strategies, such as with the ribosome biogenesis regulator LARP6 (Dermitet al., 2020), to target cell invasive activity more specifically in cancer and immune system disorders." (PMID 38628976, 2023). "SFPQ, RTN4, RICTOR, LARP6, and HELLS are all associated with cancer." (PMID 37569873, 2023). "Some cancer-related processes, such as apoptosis, oxidative phosphorylation, fatty acid metabolism and sphingolipid metabolism, were significantly enriched in the lower LARP6 expression group." (PMID 36691044, 2023). "Since enhanced ribosome biogenesis is a common feature of most high-grade carcinomas, we wondered whether the LARP6-dependent RP synthesis could be commonly upregulated in such cancers in order to boost ribosome biogenesis." (PMID 33171110, 2020).
cancer (continued). "LARP6 inhibitors are currently being developed for the treatment of fibrotic disease, but because of their direct influence on gene transcription, may also have utility in cancer treatment." (PMID 26501340, 2015). "After down‐regulation of LARP6 in the TNBC cell line, the results from the cell counting kit‐8 (CCK‐8) assay and EdU staining suggested the proliferation of the cancer cells was significantly affected." (PMID 40635123, 2025). "Taken together, we demonstrate that LARP6 serves as a dual regulator of proliferation and immune infiltration of TNBC cells instead of ER+ and HER2+ cancer cells, suggesting its potential to be the specific therapeutic target for the aggressive TNBC subtype." (PMID 40635123, 2025). "Although the role of LARP6 and ZNF267 in CRC differs from that in other tumors, it is frequent in tumor studies that gene distinctively regulates cancer development in different tumor types or even shows opposing effects." (PMID 36691044, 2023). "As emerging research uncovers the function of each LARP, it is evident that La, LARP1, LARP6, LARP7 and possibly LARP4a and 4b are dysregulated in cancer." (PMID 26501340, 2015). "We hypothesized that in cancers with strong EMT features, inhibiting LARP6 could provide a therapeutic opportunity to more specifically target ribosome biogenesis." (PMID 33171110, 2020). "Unlike La, LARP1 and LARP6, knockdown of LARP4a in cancer cells promotes rather than inhibits cancer cell migration." (PMID 26501340, 2015). "Consistently, after LARP6 knockdown, western blot results also showed reduced expression of Cyclin B1 and CDK1, which drive the cell cycle progression from G2 to M phase, indicating that LARP6 promotes the proliferation of TNBC cancer cells via regulation of the cell cycle progression." (PMID 40635123, 2025). "Importantly, although Larp6 is required for endogenous RP mRNA transport in migrating cancer cell projections, it is not expressed in CAD cells and therefore was not included in the screen." (PMID 36867563, 2023).
tumor (6 papers, 2015 to 2025). "La, LARP1 and LARP6 are upregulated and associated with tumour invasion and migration whereas LARP7 and possibly LARP4a are down-regulated in malignancy and associated with progression and metastasis." (PMID 26501340, 2015). "Our RIP-seq identified various tumor-related transcripts relevant to LARP6, which further illustrates its importance in CRC progression." (PMID 36691044, 2023). "In vivo, using a human tumour xenograft model, LARP6 acts as an oncogene, enhancing angiogenesis and tumour growth." (PMID 26501340, 2015). "The positive correlation with CD8+ T cells indicates that LARP6 might paradoxically enhance anti‐tumour immunity through cytotoxic T cell recruitment, potentially representing a compensatory mechanism activated in response to aggressive tumour growth." (PMID 40635123, 2025). "Furthermore, LARP6 is also involved in some tumor-related cellular processes, such as cell survival, angiogenesis, motility and the like." (PMID 36691044, 2023). "We preliminarily selected several genes closely related to tumor metastasis in our RIP-seq list, and studied the influence of LARP6 on these mRNA abundance." (PMID 36691044, 2023). "The expression of RNASE2 and LARP6 was slightly elevated in tumor tissue, and ANG was not collected in the Human Protein Profiles." (PMID 33589575, 2021). "Furthermore, immune infiltration analysis demonstrated significant correlations between LARP6 expression and the immune infiltration of specific immune cell populations, suggesting a potential role for LARP6 in modulating the TNBC tumour microenvironment beyond its cell‐intrinsic functions." (PMID 40635123, 2025). "Furthermore, six tumor progression genes (GNAI2, ODC1, APP, TNFRSF12A, BASP1, and LARP6) and nine migration and metastasis‐related genes (MSN, FLOT1, LAMB3, MYL9, ITGB1, FTH1, TPM4, and PMEPA1), which could explain the invasive characteristics of SCC, were identified." (PMID 40776410, 2025).
LARP6 also shares sentences with these, for which no sentence is quoted: kidney cancer (2 papers); diabetes (1); genetic disorder (1); heart failure (1); invasive ductal carcinomas (1); Obesity (1); osteogenesis imperfecta (1); pulmonary fibrosis (1); renal cell carcinoma (1).